IL6 (interleukin 6)
Diseases named in the same sentence as IL6 in open-access papers (continued):
Sharing a sentence is not in itself a finding about the gene and the disease.
gastric cancer (continued). "In our study, it was found that in all patients with gastric cancer the level of IL-6 was increased in comparison to its values obtained in the control group." (PMID 23554823, 2013). "CRP, IL-6, and IL-23 were the markers used in the assessment of inflammation in patients with gastric cancer." (PMID 23554823, 2013). "To elucidate the role of IL-6 in gastric cancer, we examined IL-6 expression in human gastric cancer tissues." (PMID 23593346, 2013). "IL-6 has been shown to enhance invasion of gastric cancer cells through sustained activation of STAT3." (PMID 24116074, 2013). "The aim of our study was to investigate the protein and mRNA levels of IL-6 and NF-κB and to analyze the correlation of these two proteins in gastric cancer patients." (PMID 23117246, 2013). "In the present study, we showed that activation of NF-κB correlates with IL-6 in human gastric cancer tissues." (PMID 23117246, 2013). "In the present study, we investigated the association of interleukin (IL)-6/STAT3 signaling pathway with T lymphocytes and clinical implication in patients with gastric cancer." (PMID 24116074, 2013). "Because these experiments showed that stromal fibroblasts expressed IL-6 in gastric cancer, we used primary human gastric fibroblasts in vitro to examine the role of IL-6 in epithelial–stromal interaction." (PMID 23593346, 2013). "Impaired tumor development in IL-6−/− mice was correlated with the decreased activation of STAT3, a factor associated with gastric cancer cell proliferation." (PMID 23593346, 2013). "Of the 21 gastric cancer cases examined, 19 (86%) expressed IL-6 (4.9–220 pg/mg protein), whereas no normal gastric mucosa sample expressed a detectable level of IL-6." (PMID 23593346, 2013). "Immunostaining of phopho-IκBα in stromal IL-6–positive gastric cancer tissues showed that NFκB is activated both in tumor cells and in stromal cells." (PMID 23593346, 2013). "In a string of studies using gp130 mutant mouse model of gastric cancer, the importance of IL-11 was highlighted and IL-6 is reported to be relatively unimportant." (PMID 23593346, 2013). "Immunohistochemical analysis of human gastritis, gastric adenoma, and gastric cancer tissues revealed that IL-6 was frequently detected in the stroma." (PMID 23593346, 2013). "In the course of gastric cancer, it is GM-CSF or Tpo through IL-6 which influences the increase in the number of platelets." (PMID 23554823, 2013). "This is consistent with our findings that IL-6 expression was markedly associated with STAT3, and they were both over-expressed in human gastric cancer." (PMID 24116074, 2013). "In our study, it was found that in all patients with gastric cancer, there is an increase of IL-6, and the reference point was the group of healthy subjects." (PMID 23554823, 2013). "In our study of patients with gastric cancer, inflammation was observed which was subsequently confirmed by the results of determinations of C-reactive protein and IL-6." (PMID 23554823, 2013). "We also compared the IL-6 expression levels in gastric cancer tissues from 21 patients with those in Helicobacter pylori–negative normal gastric mucosa tissue samples from 6 healthy individuals by ELISA analysis." (PMID 23593346, 2013). "Several studies examining IL-6 expression in human gastric cancer tissues showed that IL-6 expression was positively correlated with vascular endothelial growth factor (VEGF) expression, as well as tumor vascularity and histological grade." (PMID 23593346, 2013). "IL-6 production from fibroblasts was increased when fibroblasts were cultured in the presence of gastric cancer cell–conditioned media." (PMID 23593346, 2013). "In the present study, we investigated the effect of NF-κB on the IL-6 pathway in gastric carcinoma and their correlation with disease status and prognosis." (PMID 23117246, 2013).
gastric cancer (continued). "Recent studies suggest that the IL-6/gp130/STAT3 (interleukin-6/glycoprotein 130/signal transducer and activation of transcription 3) pathway plays a role in the development of gastric cancer." (PMID 24212943, 2011). "Lycopene treatment had significantly increased blood IL-2, IL-4, IL-10, TNF-α levels and reduced the IL-6 level in gastric cancer rats." (PMID 21686188, 2011). "Compared with the normal control rats, blood IL-2, IL-4, IL-10 and TNF-α levels were significantly reduced in the gastric cancer model rats, while blood IL-6 level was significantly increased." (PMID 21686188, 2011). "Blood IL-6 level in gastric cancer model control rats was markedly higher than that in normal control rats." (PMID 21686188, 2011). "Autocrine and paracrine interleukin (IL)-6 signaling is the principal mechanism by which Stat3 is persistently phosphorylated in epithelial tumors including breast, lung, colon and gastric cancer." (PMID 20929542, 2010). "Preoperative high IL-6 levels were proposed as a poor prognostic factor for disease recurrence and overall survival in patients with gastric cancers." (PMID 19457231, 2009). "Especially high IL-6 levels were prospected as a poor prognostic factor of disease recurrence and overall survival in patients with gastric cancer." (PMID 19457231, 2009). "Downregulation of SOCS-1 cooperates with IL-6 in the activation of JAK/STAT pathway in gastric cancer." (PMID 15354212, 2004). "In this study, we have found that IL-6 was endogenously expressed in several gastric cancer cell lines." (PMID 15354212, 2004). "Taken together, these findings suggested that SOCS-1 play an important role in the inhibition of IL-6-mediated STAT3 activation in AGS gastric cancer cell line." (PMID 15354212, 2004). "Two other smaller studies also linked serum IL-6 and survival in operable gastric cancer without perioperative treatment." (PMID 41249451, 2026). "Additionally, in the inflammatory microenvironment of gastric cancer and lung adenocarcinoma, IL-6 stimulates the JAK/STAT signaling pathway, regulates the expression of Snail, promoting the EMT process." (PMID 41019090, 2025). "IL-6 is frequently elevated in human gastric cancer and activates STAT3 signaling to promote proliferation, survival, and metastasis; the modest protective effect of IL-6 deletion suggests that other cytokines may compensate for its loss in this model." (PMID 40673273, 2025). "Additionally, a mouse study on gastric tumorigenesis induced by N-methyl-N-nitrosourea revealed that IL-6 promotes gastric cancer cell proliferation through the activation of STAT3, as demonstrated by comparing IL-6 knockout mice with wild-type mice." (PMID 40051564, 2025). "Given PPARα’s established role in restraining pro-inflammatory cytokines such as IL-6, IL-1β, and TNF-α, and the importance of inflammation in gastric cancer progression, we next assessed whether loss of PPARα elevates inflammatory mediators in GC cells." (PMID 40732023, 2025). "This gp130Y757F mutation impairs SOCS3-mediated negative feedback regulation, leading to hyperactivation of the IL-6/JAK/STAT3 pathway, which is one of the most frequently dysregulated signaling cascades in human gastric cancer and is associated with inflammation, proliferation, and immune evasion." (PMID 40673273, 2025). "The depletion of IL-6 with a neutralizing antibody or inhibition of the JAK/STAT3 pathway with the specific inhibitor AG490 significantly attenuated these phenotypes in CAF-induced gastric cancer cells." (PMID 40485724, 2025). "Rho/Rho-associated protein kinase (ROCK) pathway also plays a key role in gastric cancer cell metastasis and invasion by recruiting IQ domain GTPase activating protein 1 (IQGAP1) 13-16, while IL-6 induces gastric cancer cell invasion by activating the c-Src/RhoA/ROCK signaling pathway." (PMID 40092690, 2025). "For example, in gastric cancer cells, circRBM33 targets miR-149 to manipulate IL-6 expression." (PMID 40158127, 2025).
gastric cancer (continued). "A study of postoperative ENN intervention in patients with gastric cancer revealed that the serum levels of IL-6 and tumor necrosis factor-alpha (TNF-α) were significantly lower in the intervention group than in the control group, resulting in a lower degree of inflammation." (PMID 41393952, 2025). "Furthermore, other studies have shown that the IL-6 level is significantly elevated in the serum of patients with gastritis and peptic ulcers, and it is also expressed at higher levels in gastric cancer patients." (PMID 40143073, 2025). "A new immunosuppressive subpopulation of fibroblasts exists in gastric cancer, which can exclusively overexpress CPT1C and secrete the pro-inflammatory cytokine IL-6 to interfere with the immunosuppressive function of macrophages in gastric cancer, thereby exerting a pro-cancer effect." (PMID 39596847, 2024). "Collectively, according to our research, individuals with advanced gastric cancer who benefit from immunochemotherapy may possess decreased IL-6 and/or IL-8 blood levels." (PMID 38774604, 2024). "Moreover, the inflammatory cascade initiated by gastric cancer surgery leads to a marked escalation in the levels of interleukin-6 (IL-6) and tumor necrosis factor-alpha (TNF-α), concurrent with a diminution in the expression of immunoregulatory cytokines." (PMID 39925886, 2024). "The IL-6/STAT3 signaling pathway plays a major role in the progression of gastric cancers." (PMID 38967742, 2024). "Key metabolites such as linoleic acid, panaxynol, methyl linoleate, palmitoleic acid, and oleic acid have been identified to interact with critical targets in gastric cancer, including EGFR, MAPK1, MAPK3, and IL-6, significantly inhibiting the proliferation of gastric cancer cells." (PMID 39193331, 2024). "Our findings demonstrated a remarkably high predictive ability to forecast clinical efficacy in patients with advanced gastric cancer receiving anti-PD-1 mAb treatment, especially when IL-6, IL-8, and CEA are combined (AUC: 0.872), underscoring the robustness of these biomarkers." (PMID 38774604, 2024). "The genes targeted by AMK in the context of gastric cancer include apoptosis regulator Bcl-2 (BCL2), catenin beta 1 (CTNNB1), B-cell stimulatory factor 2 (IL6), mutated in multiple advanced cancers 1 (PTEN), proto-oncogene (SRC), and tumor necrosis factor ligand member 2 (TNF)." (PMID 38612999, 2024). "The expression levels of IL-6, IL-17, FoxP3, and TGF-β1 in cancerous tissues were significantly higher than those in the control group and were associated with clinical staging of gastric cancer." (PMID 39676857, 2024). "Li Xu and colleagues reported that interferon-induced transmembrane proteins (IFITM) in gastric cancer can regulate the expression and secretion of interleukin 6, which in turn can increase the expression of IFITM through feedback, thus mediating the growth of gastric cancer and lung metastasis." (PMID 39309860, 2024). "Also, IL-6/STAT3 signaling pathway was reported to play a major role in the progression of gastric cancers." (PMID 38967742, 2024). "In gastric cancer patient blood, IL-6 concentration is higher in stage 4 than in stages 2 and 3, so IL-6 may be related to the malignancy of gastric cancer such as metastasis and cancer severity." (PMID 38612999, 2024). "Moreover, the extract targets key proteins, including EGFR, SCR, and IL6, to suppress the progression of gastric cancer, thereby synergistically inhibiting cancer development." (PMID 38611946, 2024). "In the field of gastric cancer, researchers have found that elevated IL-6 release at the tumor site may be crucial in encouraging the polarization of M2 macrophages." (PMID 39251966, 2024). "IL-6 can activate the STAT3 pathway, which is associated with gastritis and gastric cancer." (PMID 38978704, 2024).
gastric cancer (continued). "As one of the major elements in tumor stroma, gastric cancer‐derived mesenchymal stromal cells (GC‐MSCs) was reported to trigger M2 polarization through activation of the JAK2/STAT3 signaling pathway via high secretion of IL‐6/IL‐8." (PMID 38349050, 2024). "Compared with those in the naloxone group, the expression levels of TLR4 (P < 0.05) in gastric cancer tissue in the naloxone group were greater; however, the expression levels of IL-6 (P < 0.01) and TNF-α (P < 0.01) in the naloxone group were greater than those in the nonnaloxone group." (PMID 38720250, 2024). "Another study demonstrated that CAF-mediated activation of the JAK-STAT signaling pathway could confer chemotherapy resistance to gastric cancer cells, while IL-6 secreted by CAFs could protect gastric cancer cells through a paracrine signaling pathway." (PMID 39765634, 2024). "Likewise, researchers found that IL-6 produced by CAFs promotes chemoresistance through the JAK-STAT3 signaling pathway and that targeting IL-6 is a strategy to improve the therapeutic efficacy of chemotherapy in gastric cancer." (PMID 38459511, 2024). "Confirmation of the results in a larger group of patients seems to be essential from a clinical point of view, bearing in mind that IL-6 plays a significant role in gastric cancer biology, particularly in metastasis formation and in the mechanism of chemotherapeutic resistance." (PMID 38398148, 2024). "While IL-6 is commonly regarded as a pro-inflammatory cytokine that is increased in H. pylori gastritis and gastric cancer, the cytokine also has anti-inflammatory effects, including promoting alternative activation of macrophages to an anti-inflammatory phenotype." (PMID 38014984, 2024). "In patients with advanced gastric cancer who receive platinum-based chemotherapy, serum IL-8, but not IL-6 level, was associated with poor clinical outcomes." (PMID 38562556, 2024). "Follow-up studies further confirmed that IL6 may be secreted by gastric cancer-derived mesenchymal stromal cells." (PMID 39251966, 2024). "IL-6 is an important pro-angiogenic factor in gastric cancer through the induction of the VEGF." (PMID 38398148, 2024). "In vitro experiments showed that CD66b+ neutrophils could promote the migration and invasive ability of gastric cancer cell lines by secreting inducible epithelial-mesenchymal transition-associated factors (e.g., TGF-β and IL-6)." (PMID 39346904, 2024). "Therefore, we proposed the existence of hypoxia– LOX+fibroblast–IL6–monocyte– M2 macrophage loop, which induced the progression of gastric cancer and created a specific immunosuppressed state." (PMID 39251966, 2024). "In addition, IL-6 protects the mucosa against ulceration and upregulate mucin 4 expression in cultured gastric cancer cell lines." (PMID 37658354, 2023). "The molecular mechanism of action of Les-4367 is associated with the induction of extrinsic and intrinsic apoptotic pathways, decreased MMP-2 and ICAM-1 concentrations—which are involved in the invasion of gastric cancer—as well as reduced levels of the pro-inflammatory cytokine IL-6." (PMID 37047765, 2023). "In addition, the level of Interleukin 6 (IL-6) induction in H. pylori-infected cases closely correlates to gastric cancer incidence in the corresponding global regions." (PMID 37006300, 2023). "Moreover, BA dose-dependently inhibited the GRP78-mediated secretion of TGF-β, thereby suppressing macrophage polarization, IL-6 secretion, and IL-6-mediated gastric cancer stemness." (PMID 36838713, 2023). "Similarly, in the inflammatory microenvironment of gastric cancer, Helicobacter pylori activates downstream inflammatory factors, like IL-6, IL-10, and COX-2, through TLRs (mainly TLR2 and TLR4), thus initiating a series of inflammatory responses." (PMID 37153547, 2023). "We then investigated the inhibitory effect of IL-6 reduction on gastric-cancer cell stemness." (PMID 36838713, 2023). "Estrogen enhances IL-6 production by CAFs in gastric cancer." (PMID 37509283, 2023).
gastric cancer (continued). "Furthermore, studies have demonstrated that levels of IL-1β, IL-6, and IL-8 in gastric cancer tissues are significantly elevated in H. pylori-positive cases compared to H. pylori-negative cases." (PMID 37729185, 2023). "In addition, IL-6 stimulated gastric cancer stemness by activating the STAT3 signaling pathway and upregulating the stemness-related marker OCT4." (PMID 36838713, 2023). "Characterisation of secreted factors in co‐cultures, rather than the corresponding mono‐cultures, is a relatively uncharted area, and the co‐culture may only be compared to one cell type, as in a recent study on IL‐6 in gastric cancer." (PMID 36608258, 2023). "Through the analysis of serum IL‐6 levels in patients with gastric cancer, it was found that serum IL‐6 could be an independent predictor." (PMID 37324920, 2023). "High expression of DYNC1I1 was associated with poor prognosis and promoted the proliferation and migration of gastric cancer cells by upregulating IL-6 expression, which suggests that DYNC1I1 may be a potential therapeutic target for gastric cancer." (PMID 37628612, 2023). "In addition, the IL6/JAK/STAT3 pathway was reported to be upregulated in EBV-associated epithelial cancers such as Nasopharyngeal carcinoma, gastric carcinoma, and oral squamous cell carcinoma." (PMID 37297008, 2023). "IL-6 has been attributed to invasive tumour function in pancreatic, bladder and gastric cancer." (PMID 35022523, 2022). "IL-6 is a pro-inflammatory cytokine that promotes the growth and progression of gastric cancer." (PMID 36140220, 2022). "In order to have a more comprehensive understanding of the association of perioperative inflammatory states with long-term outcomes, the nonlinear association between the serum IL6_0 and TNFα_0 levels with survival in patients with gastric cancer was explored." (PMID 35859928, 2022). "Moreover, the serum IL-6 and TNFα levels were decreased, and the serum IL-2, IL-4 and IL-10 levels were increased in gastric cancer mice after tea polysaccharides treatment." (PMID 36505461, 2022). "Both IL-6 and IL-18 are predictors of prognosis in gastric cancer patients." (PMID 35892729, 2022). "Furthermore, high levels of IL-6 were also related to poor prognosis with recurrence and the overall survival rates of gastric cancer patients." (PMID 36140220, 2022). "Plasma interleukin-6 (IL-6) was shown to be increased in gastric cancer patients." (PMID 35566016, 2022). "The IL6-JAK-STAT3 signaling pathway is dysregulated in stomach cancer." (PMID 35712475, 2022). "The increase of IL-6 was observed in the serum of gastric cancer patients by different groups." (PMID 36185270, 2022). "In gastric cancer, the NF-κB signalling pathway could be activated after helicobacter pylori infection, which upregulates the expression of IL-1, IL-6, TNF-α, and endothelial growth factor, thereby activating the inflammasome and triggering cell pyroptosis." (PMID 36039017, 2022). "miR-98-5, belonging to the miRNA family and being involved in many regulatory processes, was reported to have a binding site to Interleukin-6 (IL-6); IL-6 is a cytokine that modulates the generation of Th17 cells from native T cells, and is also overexpressed in gastric cancer." (PMID 35887090, 2022). "In another study, CAF-induced activation of the JAK-STAT signaling has been proposed to confer chemoresistance in gastric cancer cells, while interleukin-6 (IL-6) was identified as a CAF-specific secretory protein that protects gastric cancer cells via paracrine signaling." (PMID 35326670, 2022). "Furthermore, resveratrol reduced the activation of matrix metalloproteinases IL-6-induced cancer cell invasion in a gastric cancer cell line model." (PMID 35566016, 2022). "In gastric cancer, Zhao and colleagues indicated that IL6 could promote proliferation, invasion, and lymphangiogenesis by regulating the JAK/STAT3/VEGF-C signaling." (PMID 36276992, 2022).